RN7SL370P (RNA, 7SL, cytoplasmic 370, pseudogene)
Gene: Miscellaneous RNA gene on chromosome 1 (77,645,324 to 77,645,618, forward strand). Ensembl gene ENSG00000243437.
Homologues: Orthologues: chimpanzee Metazoa_SRP (98% identical), macaque Metazoa_SRP (89% identical). Paralogues in human: RN7SL1 (83% identical), RN7SL2 (83% identical), RN7SL3 (82% identical), RN7SL448P (80% identical), RN7SL230P (80% identical), RN7SL7P (79% identical), RN7SL45P (79% identical), RN7SL186P (79% identical), RN7SL664P (79% identical), RN7SL799P (79% identical), RN7SL126P (78% identical), RN7SL480P (78% identical), and 700 more.